PARTICL (promoter of MAT2A antisense radiation-induced circulating long non-coding RNA)
Synonyms: PARTICLE
Gene: Long non-coding RNA gene on chromosome 2 (85,534,705 to 85,539,110, reverse strand). Ensembl gene ENSG00000286532.
Diseases named in the same sentence as PARTICL in open-access papers:
PARTICL is named in the same sentence as 2 diseases in open-access papers, as found by Europe PMC text mining. Sharing a sentence is not in itself a finding about the gene and the disease.
PARTICL shares sentences with these, for which no sentence is quoted: tumor (2 papers); osteosarcoma (1).